RNU6-1330P (RNA, U6 small nuclear 1330, pseudogene)
Gene: Small nuclear RNA gene on chromosome 5 (74,779,309 to 74,779,413, forward strand). Ensembl gene ENSG00000199645.
Homologues: Orthologues: chimpanzee U6 (100% identical), macaque U6 (92% identical), pig U6 (86% identical), guinea pig U6 (85% identical), guinea pig U6 (84% identical), dog U6 (81% identical). Paralogues in human: RNU6-1011P (91% identical), RNU6-11P (91% identical), RNU6-12P (91% identical), RNU6-13P (91% identical), RNU6-26P (91% identical), RNU6-31P (91% identical), RNU6-32P (91% identical), RNU6-37P (91% identical), RNU6-949P (91% identical), RNU6-1 (90% identical), RNU6-15P (90% identical), RNU6-166P (90% identical), and 1286 more.